C3AR1 (complement C3a receptor 1)
Description:
Receptor for the chemotactic and inflammatory peptide anaphylatoxin C3a, stimulating chemotaxis, granule enzyme release and superoxide anion production. Ligand binding causes a conformation change that triggers signaling via guanine nucleotide-binding proteins (G proteins) and modulates the activity of downstream effectors, such as adenylate cyclase. C3AR1 is coupled to G(i)/G(o) (GNAI1 or GNAO1) G alpha proteins and mediates inhibition of adenylate cyclase.
Synonyms: C3AR; AZ3B; HNFAG09
Tractability: Small molecule: a structure with a bound ligand is known; a high-quality ligand is known; it belongs to a druggable protein family. Antibody: its Gene Ontology location is reachable by antibodies, with high confidence; UniProt places it where antibodies can reach, with medium confidence; UniProt predicts a signal peptide or a membrane-spanning region. PROTAC: its protein half-life has been measured; a small molecule that binds it is known.
Target class: Family A G protein-coupled receptor; Anaphylatoxin receptor family; Membrane receptor; Anaphylatoxin receptor; Peptide receptor (family A GPCR)
Chemical probes: CHEMBL1170026
Gene: Protein-coding gene on chromosome 12 (8,056,844 to 8,066,374, reverse strand). Ensembl gene ENSG00000171860.
Subcellular location: Cell membrane
Pathways (Reactome):
Immune System: Neutrophil degranulation; Regulation of Complement cascade
Signal Transduction: G alpha (i) signalling events; Peptide ligand-binding receptors
Disease: Purinergic signaling in leishmaniasis infection
Gene Ontology:
Molecular function: complement component C3a receptor activity; G protein-coupled receptor activity; protein binding; complement component C5a receptor activity; complement receptor activity
Biological process: adenylate cyclase-inhibiting G protein-coupled receptor signaling pathway; calcium-mediated signaling; complement receptor mediated signaling pathway; blood circulation; G protein-coupled receptor signaling pathway; inflammatory response; phospholipase C-activating G protein-coupled receptor signaling pathway; positive regulation of cytosolic calcium ion concentration; chemotaxis; complement component C5a signaling pathway; positive regulation of angiogenesis; positive regulation of immune system process; positive regulation of macrophage chemotaxis; positive regulation of neutrophil chemotaxis; positive regulation of vascular endothelial growth factor production
Cellular component: plasma membrane; azurophil granule membrane; specific granule membrane; membrane
Genetic constraint (gnomAD): Loss-of-function variants: 1 observed, 2.63 expected, observed/expected ratio (o/e) 0.38, 90% interval 0.13 to 1.58. That is too few expected variants to judge how well the gene tolerates losing a copy. Missense variants: 579 observed, 616.47 expected, observed/expected ratio (o/e) 0.94, 90% interval 0.88 to 1.01. Synonymous variants: 208 observed, 237.46 expected, observed/expected ratio (o/e) 0.88, 90% interval 0.78 to 0.98.
Homologues: Orthologues: chimpanzee C3AR1 (99% identical), macaque C3AR1 (89% identical), dog C3AR1 (71% identical), rabbit C3AR1 (67% identical), pig C3AR1 (66% identical), mouse C3ar1 (65% identical), guinea pig C3AR1 (60% identical), rat C3ar1 (60% identical), tropical clawed frog c3ar1 (32% identical), zebrafish c3ar1 (26% identical). Paralogues in human: CMKLR1 (26% identical), C5AR1 (25% identical), FPR2 (25% identical), FPR1 (24% identical), FPR3 (24% identical), GPR33 (22% identical), C5AR2 (21% identical), GPR32 (21% identical).
Diseases named in the same sentence as C3AR1 in open-access papers:
C3AR1 is named in the same sentence as 225 diseases in open-access papers, as found by Europe PMC text mining. Sharing a sentence is not in itself a finding about the gene and the disease. The quoted sentences say what the papers report.
Obesity (24 papers, 2006 to 2025). Accumulation of substantial excess body fat. "Interest in TLQP-21 has recently been renewed following the discovery of a cognate receptor C3aR1, which has been implicated in a number of diseases including obesity and diabetes." (PMID 31465472, 2019). "This in fact was the case for each of the three genes (Tgfbr2, C3ar1 and Zfp90) we recently reported as being causal for obesity in the BXD cross." (PMID 16886998, 2006). "In mice, by CIT analysis and validation studies using genetically engineered animals, Zfp90 (zinc finger protein 90), C3ar1 (complement component 3a receptor 1) and Tgfbr2 (transforming growth factor, beta receptor II) have been identified as new QTGs involved in susceptibility to obesity." (PMID 29186889, 2017). "Our findings in macrophage-specific C3aR1 KO mice contrast with prior observations in whole-body C3aR1 KO mice, which are protected from diet-induced obesity, have improved glucose tolerance, and exhibit decreased hepatic steatosis." (PMID 39773465, 2025). "Several studies have reported opposing roles of adipsin and C3aR1 on hepatic steatosis in diet-induced obesity." (PMID 39773465, 2025). "Other work has suggested possible compensatory effects from its sister anaphylatoxin receptor C5aR1, with increased cold-induced adipocyte browning and attenuated diet-induced obesity seen in C3aR1/C5aR1 double KO mice." (PMID 39773465, 2025). "Several studies show marked though opposing roles of adipsin and C3aR1 on systemic glucose homeostasis in diet-induced obesity." (PMID 38713526, 2024). "C3AR1-knockout mice are transiently resistant to diet-induced obesity and are protected against high-fat diet-induced insulin resistance." (PMID 36712250, 2022). "C3AR1 is highly expressed in AT in the setting of obesity and atherosclerosis through the inflammatory response pathway." (PMID 32684073, 2020). "The recent discovery that TLQP-21 is the natural agonist for the complement 3a receptor 1 (C3aR1) has revived interest in this peptide as a potential drug target for obesity." (PMID 31465472, 2019). "The recent discovery that TLQP-21 is a natural agonist for the complement 3a receptor 1 (C3aR1) has stimulated interest in this peptide as a potential drug target for obesity." (PMID 31465472, 2019). "We were able to further confirm the notion, that obesity alters satellite cell numbers and negatively affects the expression levels of Ankrd1, C3ar1, Ccl8, Mpeg1, and Myog, as seen in our qPCR results." (PMID 29922174, 2018). "C3aR1 mediates the functions of insulin by modulating insulin resistance, obesity and macrophage function." (PMID 27920259, 2017). "The C3ar1-expressing cell types that promote obesity and MASLD remains to be determined." (PMID 39773465, 2025). "This raises the possibility that the lower levels of hepatic steatosis and insulin resistance previously observed in the whole body C3aR1 KO mice may be secondary to protection from obesity." (PMID 39773465, 2025). "C3aR1 knockout abolished the TLQP-21–induced anti-obesity effect seen in wild mice." (PMID 38071217, 2023). "In addition, although there is no direct evidence linking C3ar1 to obesity, indirect data from its ligand C3a suggest a relationship between C3ar1 and obesity‐related features, indicating that C3aR1 is a prospective obesity target." (PMID 38045624, 2023). "C3AR1 activation can enhance lipolysis induced by adrenaline, which may be a good way to treat obesity." (PMID 34093637, 2021). "The TLQP-21-induced anti-obesity effect is prevented by germline C3aR1 knockout in mice." (PMID 34626205, 2021). "Finally, and consistent with the effect seen in adipocytes, C3aR1 knockout prevented the TLQP-21-induced anti-obesity effect seen in wild-type mice." (PMID 34626205, 2021).
Obesity (continued). "Interestingly, obese mice display low levels of TLQP-21 and increased expression of C3aR1, whereas C3aR1 knock-out (KO) mice are transiently resistant to diet-induced obesity and are protected against insulin resistance induced by a high-fat diet." (PMID 31878142, 2019). "We applied the Attie Lab Diabetes database to verify the hub gene mRNA levels in obesity, which indicated that expression of TYROBP, TLR8, FCER1 G, HCK, NCF2, CTSS and C3AR1 was significantly up-regulated in 10-week obese mice as compared to the lean group." (PMID 32684073, 2020). "However, whole-body deletion of C3aR1 decreases macrophage infiltration and activation in adipose tissue, protects from HFD-induced obesity and glucose intolerance, and decreases hepatic steatosis and inflammation." (PMID 39773465, 2025). "In both our macrophage- and Kupffer-cell-specific C3aR1 KO mice, which had similar degrees of obesity compared to controls, there was no detectable effect on liver steatosis or fibrosis despite the near abrogation of C3ar1 expression." (PMID 39773465, 2025). "Overall, inflammation may play the role of a bridge between obesity and Alzheimer’s disease, and the four hub genes above (MMP9, PECAM1, C3AR1, and IL1R1) are critical to this." (PMID 36568118, 2022). "Protection from diet-induced obesity in whole-body C3aR1 KO mice may be mediated by a non-macrophage cell type, since our macrophage-specific C3aR1 KO mice were not afforded this protection." (PMID 39773465, 2025). "(C) Analysis of CFD and C3AR1 expression from liver biopsy samples in patients with MASH, MASLD, obesity without MASLD, and age-matched healthy controls (n=12–16 per group, Welch t test with Holm-Šídák correction for multiple comparisons)." (PMID 39773465, 2025).
Sepsis (24 papers, 2013 to 2026). Sepsis is defined as life-threatening organ dysfunction caused by a dysregulated host response to infection. "Matrix metallopeptidase 9 (MMP9) and Complement C3a Receptor 1 (C3AR1), immune infiltration-associated biomarkers of sepsis, have been reported to be related with the prognosis of sepsis patients." (PMID 35265105, 2022). "Furthermore, C3AR1 has been closely associated with immune responses, such as sepsis and Alzheimer’s disease (AD)." (PMID 39062086, 2024). "C3AR1, as the orphan G protein-coupled receptor for the allergic toxin C3a released during complement system activation, plays a crucial role in immune responses, particularly implicated in immune infiltration in sepsis." (PMID 39108264, 2024). "For example, C3AR1 is associated with immune infiltration in sepsis." (PMID 33748161, 2021). "If the pro-inflammatory response induced by macrophages cannot be properly controlled, it may result in a cytokine storm, leading to macrophage apoptosis and ultimately causing immunosuppression.Thus,C3AR1 may contribute significantly to the pathophysiology of sepsis." (PMID 38678059, 2024). "Integrating the results of these approaches, C3AR1 and SLPI were identified as key sepsis-associated genes." (PMID 40421173, 2025). "Studies have found that core genes ITGAM and C3AR1 are expressed at higher levels in the plasma of sepsis patients, and through clinical translation, they can become new targets for the diagnosis and treatment of sepsis." (PMID 41209006, 2025). "The expression level of C3AR1 efficiently reflects the immune microenvironment during sepsis, offering potential guidance for immune-modulating agents to achieve immune homeostasis." (PMID 40421173, 2025). "Considerable evidence supports a strong association between C3AR1 and SLPI and sepsis, highlighting their significance in sepsis pathophysiology." (PMID 40421173, 2025). "We found positive correlation between expression of IL-1β and C3AR1 only in patients suffering from sepsis." (PMID 38236896, 2024). "The “Sepsis Metascore” subpanel on another hand, consists of a sepsis-specific transcripts including CEACAM1, C3AR1, GNA15, and HLA-DPB1 which have previously been linked to sepsis." (PMID 35186993, 2022). "Together, these results indicate that expression of IL-1β, the IL-1β receptor, and the complement 3 receptor transcripts are induced in humans suffering from sepsis and that positive correlation between expression of IL-β and C3AR1 occurs only in sepsis patients." (PMID 38236896, 2024). "While we show a correlation between expression of IL-1β and the complement receptor C3AR1 in humans suffering from sepsis, it will need to be tested whether this is the mechanism which results in fatalities from septicaemia in humans." (PMID 38236896, 2024). "Thus, C3AR1 appears to play a critical role in sepsis pathophysiology and may serve as a prognostic marker or therapeutic target." (PMID 40421173, 2025). "Our findings identify C3aR1 as a key molecular hub orchestrating macrophage-neutrophil crosstalk in SIMI and highlight its potential as a therapeutic target for mitigating sepsis-induced cardiac complications." (PMID 42002824, 2026). "The results indicated that ITGAM, CD44, C3AR1, and IL2RG exhibited significantly higher expression in the sepsis group compared to the SIRS group." (PMID 38678059, 2024). "The expression levels of C3AR1 and SLPI were examined in sepsis datasets." (PMID 40421173, 2025). "Similarly, in the validation datasets GSE69528 and GSE95233, the relative expression of C3AR1 and SLPI in advanced sepsis was significantly higher than in the control group." (PMID 40421173, 2025). "We found higher levels of IL-1β, C3AR1, and IL1R1 transcripts in patients with sepsis and a positive correlation between expression levels of IL-1β and C3AR1 in sepsis patients but not healthy controls." (PMID 38236896, 2024).
Sepsis (continued). "Furthermore, a meta-analysis identified four genes, namely ITGAM, CD44, C3AR1, and IL2RG, which were highly expressed in the sepsis group compared to the normal group (P < 0.05)." (PMID 38678059, 2024). "Similarly, C3AR1, a marker of CD16+ monocytes with a macrophage-like morphology and heightened cytokine production, is significantly upregulated and identified as a potential therapeutic target in sepsis." (PMID 40761792, 2025).
Alzheimer disease (22 papers, 2015 to 2025). A progressive, neurodegenerative disease characterized by loss of function and death of nerve cells in several areas of the brain leading to loss of cognitive function such as memory and language. "C3ar1 has been implicated in mediating synaptic plasticity and phagocytosis by microglia in cell culture and a mouse model relevant to Alzheimer’s disease, but has not yet been in models of glaucoma." (PMID 33176797, 2020). "Inactivated C3AR1 could reverse an abnormal immune network in Alzheimer's disease." (PMID 33748161, 2021). "C3AR1 depletion inhibits oxidative stress in microglia and mitigates HIF-1α-induced metabolic damage, thereby ameliorating cognitive dysfunction in Alzheimer’s disease." (PMID 40939011, 2025).
breast carcinoma (21 papers, 2007 to 2025). "Specifically, we found that low expression levels of C3AR1 are associated with resistance to chemotherapy in colorectal and breast cancer but increased the drug sensitivity in GBM and ovarian cancer cohorts." (PMID 34439277, 2021). "A low level of C3AR1 expression indicated chemotherapy resistance in colorectal and breast cancer, but increased sensitivity to chemotherapy in glioblastoma multiforme (GBM) and ovarian cancer." (PMID 37907575, 2023). "Adipsin is another adipokine upregulated in ASCs derived from obese patients, which stimulates the cell surface receptor complement C3a receptor 1 (C3aR) and the cleavage of factor B, leading to proliferation of breast cancer cells." (PMID 36010901, 2022). "The graphical presentation of expression result from cBioportal revealed that the maximum expression of C3AR1 was found in breast cancer samples followed by ovarian then cervical cancers and minimum in uterine or endometrial cancers." (PMID 31879572, 2019). "ITGAM and ITGAX are mainly involved in systemic lupus erythematosus, while TYEOBP and C3AR1 have been studied in the context of breast cancer." (PMID 31740624, 2019).
melanoma (20 papers, 2019 to 2025). A malignant, usually aggressive tumor composed of atypical, neoplastic melanocytes. "Complement component 3a receptor 1 (C3aR1) antagonists restrained neutrophil mobilization, and melanoma-bearing C3aR1-deficient mice had reduced tumor growth and frequency of heme oxygenase 1 (HO-1) expressing monocytic blood precursors of HO-1+ TAMs." (PMID 35158779, 2022). "Previous studies have demonstrated the involvement of C3AR1 mRNA in various diseases, including multiple myeloma, colon cancer, and melanoma." (PMID 39062086, 2024). "The predictive model created in this work comprises five inflammatory response-related genes: C3AR1, CXCL10, EIF2AK2, EMP3, and ICAM1, all of which are all overexpressed in melanoma tissue and are associated with a poor prognosis." (PMID 35982458, 2022). "As expected, we found that high expression of C3, C5, C3AR1, and C5AR1 is associated with worse ICB outcomes in melanoma and bladder cancer." (PMID 34439277, 2021). "We found that C3, C3AR1, and C5AR1 are associated with T-cell dysfunction phenotypes in two (GSE12417_GPL570 and TCGA melanoma) of the five datasets enumerated." (PMID 34439277, 2021). "Although the effect of C3AR1 expression on melanoma is unknown, a study by Nabizadeh discovered that in the absence of complement C3aR (receptor for complement C3a), the development and growth of B16-F0 melanoma were inhibited in mice." (PMID 35982458, 2022). "In conclusion, the complement components C3, C5, C3AR1, and C5AR1 demonstrated a context-dependent association with tumor immune evasion, prognosis, and therapy response with high implicative value in melanoma, colorectal, brain, breast, stomach, and renal cancer." (PMID 34439277, 2021). "C3AR1 is a hub mRNA for multiple myeloma, colon cancer and melanoma." (PMID 33748161, 2021). "CXCL8, CXCL9, CXCL10, CCL27, and C3AR1 have known immunomodulatory roles in melanoma." (PMID 35008167, 2021).
Cognitive impairment (12 papers, 2018 to 2026). Abnormal cognition is characterized by deficits in thinking, reasoning, or remembering. "Interestingly, the cognitive impairments were attenuated by the genetic deletion of c3ar1 or via the administration of SB290157, a potent C3aR antagonist." (PMID 34566627, 2021). "Furthermore, genetic deletion of C3ar1 and C3aR antagonist inhibited aberrant microglia activation and microglia redistribution to myelin and subsequently reversed white matter injury and cognitive deficits." (PMID 31903107, 2020).